BRAF (B-Raf proto-oncogene, serine/threonine kinase)
Diseases named in the same sentence as BRAF in open-access papers (continued):
Sharing a sentence is not in itself a finding about the gene and the disease.
cancer (continued). "Solid structures formed by Caco2-BRAF cells comply with the association of mutation in the BRAF oncogene, with poorly differentiated carcinomas containing such structures and having poor patient survival." (PMID 31545494, 2019). "This method can be a screening tool for BRAF V600E mutation as it allows the detection of small number of cancer cells carrying mutation." (PMID 29879227, 2018). "More than 50% of PTC patients present with LNM and BRAF V600E is the most common mutation identified in this cancer." (PMID 29713312, 2018). "PLX4302 is an inhibitor of the BRAFV600E mutation for the treatment of cancers harboring activated BRAF mutations." (PMID 30104528, 2018). "A well-known example is the treatment of cancers harboring a BRAF mutation with Vemurafenib, an inhibitor designed to target specifically the mutated form of BRAF." (PMID 31763498, 2018). "It is important to note that BRAF mutations are strongly associated with CIMP-high cancer which, in turn, correlates strongly with MSI-high cancer." (PMID 29652830, 2018). "Recent studies that have utilised genome-wide methylation arrays have confirmed that those cancers with the most frequent and widespread methylation do significantly correspond with the BRAF mutation and MLH1 methylation." (PMID 30598662, 2018). "Ultra-short PCR assay with forward mutation-specific primers is potentially useful to detect BRAF V600 mutations in highly fragmented DNA specimens from cancer patients." (PMID 29879227, 2018). "Since the advent of less restricted diagnostic methods, such as next-generation sequencing (NGS), the proportion of non-V600 BRAF mutations identified in different cancer types, including NSCLC, has grown." (PMID 29662630, 2018). "DUSP5 levels have been reported to be elevated in some cancers, particularly in the context of BRAF mutations." (PMID 29379130, 2018). "Trametinib is a highly specific and potent MEK1/2 inhibitor that suppresses the activity of RAS/ERK signalling, which is expected to inhibit the growth of cancers with the RAS/BRAF mutation." (PMID 30185207, 2018). "The recently developed monoclonal VE1 antibody has permitted the use of IHC to assess BRAF V600E mutation status in the FFPE tissue in cancers." (PMID 29879227, 2018). "BRAF is a major target of therapies, as it is the most frequently mutated protein kinase in human cancers." (PMID 29565994, 2018). "Often, these factors are dependent on the genetic background of the cancer with the BRAF mutation occurring in microsatellite stable cancers conferring a significantly more aggressive phenotype." (PMID 30598662, 2018). "This evidence raises expectation for the clinical trial of trametinib or CH5126766 plus statins in cancer patients with BRAF or RAS mutation." (PMID 29731968, 2018). "Across several cancer types, the vast majority of BRAF mutations occur at the V600 amino acid residue where a transversion of a thymidine to adenosine occurs at nucleotide 1799, resulting in conversion of valine to glutamate." (PMID 30598662, 2018). "A discovery cohort (n = 187) and a validation cohort (n = 801) were analysed for associations with BRAF mutations, clinicopathological characteristics and cancer-specific survival (CSS)." (PMID 29988110, 2018). "Crosstalk activation of the PI3K pathway via signalling through KRAS as well as mutations in PIK3CA and PTEN that occur in 17% and 21% of BRAF mutant cancers, respectively, can render cancer cells resistant to MAPK inhibition." (PMID 30598662, 2018). "Two studies that examined large cohorts of stage II and III CRC reported that MSS cancers with a BRAF mutation had a worse prognosis compared to those with a KRAS mutation, and this was independent of disease stage and adjuvant treatment." (PMID 30598662, 2018).
cancer (continued). "Serrated pathway cancers mutate BRAF early in tumourigenesis due to their presence in the earliest form of precursor lesions." (PMID 30598662, 2018). "In line with sporadic MSI-H CRCs, the IBD-associated cancers displayed frequent BRAF and TGFBR2 mutations." (PMID 29652830, 2018). "Our study justifies the further exploration of type II pan-RAF inhibitors in combination with Trametinib against lung (and probably other) cancers harboring different types of BRAF mutations." (PMID 29662630, 2018). "Deregulation of the pathway is associated with the presence of BRAF mutations in human cancer, the most common being V600EBRAF, although structural rearrangements, which remove N-terminal regulatory sequences, have also been reported." (PMID 30603699, 2018). "The same number of BRAF mutations in PDAC were also reported in the most recent study from the cancer genome atlas research network." (PMID 29329208, 2018). "So far, there is no report regarding the involvement of SLC7A3 in cancers, for the first time, our study found that SLC7A3 expression was associated with ETE, higher cancer stage, BRAF, RAS mutation, and mortality in PTC." (PMID 30558624, 2018). "In human cancers, mutations in BRAF are more frequent than mutations in either ARAF or CRAF, most commonly through the acquisition of nucleotide substitutions such as that encoding the V600EBRAF mutant." (PMID 30603699, 2018). "BRAF mutation is associated with poor clinical outcome of patients with malignant tumours, and mediates resistance to chemotherapy and targeted therapy." (PMID 29755114, 2018). "This indicates that the detrimental prognosis seen in late-stage MSI cancers is driven by presence of the BRAF mutation." (PMID 30598662, 2018). "CIMP-positive, BRAF mutant/MSS cancers were found to harbour a hotspot mutation at R132 in IDH1 which causes CIMP in glioma." (PMID 30598662, 2018). "We used trametinib in this study as among MEK inhibitors, trametinib is approved by the Food Drug Administration and is used alone or in combination with dabrafenib to treat certain types of cancer in individuals who harbor a “BRAF” mutation." (PMID 30509235, 2018). "Conventional treatment based on organ site, with molecular subtypes, cannot be entirely replaced by molecular nosology, e.g., BRAF-mutated cancers." (PMID 29764494, 2018). "We first developed assay to detect common BRAF V600 mutations, i.e. V600E (c.1799T>A or c.1799_1800delTGinsAA) and V600K (c.1798_1799delGTinsAA), which indicate a response to cancer treatment by BRAF inhibitors." (PMID 29879227, 2018). "BRAF mutations are thought to be early events in CIMP cancers, inhibiting normal apoptosis of colonic epithelial cells." (PMID 30071442, 2018). "Although rare, over 50 different translocations involving the BRAF gene have been detected in human cancers, many associated with removal of the BRAF N-terminal regulatory domain and expression of novel fusion proteins with the BRAF C-terminal kinase domain." (PMID 30603699, 2018). "The findings contained herein reveal that a number of off‐target effects of dabrafenib, such as NEK9 and CDK16, are inhibited at clinically achievable doses and that this likely contributes to its efficacy, particularly in cancers that lack BRAF mutations." (PMID 29112787, 2018). "PLX4032 is an inhibitor of the BRAFV600E mutation and used for the treatment of cancer cells harboring activated BRAF mutations." (PMID 30104528, 2018).
cancer (continued). "Expression of mutated BRAF is described for approximately 50% of all melanomas and is also observed in varying prevalence in other types of cancers, e.g. colorectal cancer, non-small cell lung cancer and gastric cancer." (PMID 28418885, 2017). "YAP silencing enhanced the response to RAF and MEK inhibitor in a wide spectrum of BRAF-mutated cancer cell lines, and patients who have BRAF-mutated tumors with lower YAP expression respond better to treatment with RAF and MEK inhibitor." (PMID 28035075, 2017). "The most common BRAF mutation, found in over 90% of human cancers, is a glutamic acid for valine substitution at codon 600 in exon 15 (V600E), leading to constitutive activation of the MAPK pathway." (PMID 28583095, 2017). "Pooled cancer prevalence in reported studies concerning both BRAF mutation and TSHR mRNA were rather high (45% and 44% respectively), comparable to the highest value observed and reported in South Korea (47.4%), suggesting possible selection bias." (PMID 28472764, 2017). "Genetic alterations in RAS and BRAF are the driver mutations in cancer which is associated with resistance to current therapies and disease recurrence in various types of cancer, including CRC." (PMID 29383184, 2017). "Shortly after the discovery of the RAF gene family, it was found that activating mutations in the BRAF gene, encoding the B-raf serine-threonine protein kinase, play an oncogenic role in cancer development." (PMID 28282860, 2017). "Our screening and validation analyses identified miR-193a-3p as one possible BRAF-mutant specific miRNA; however, the underlying mechanisms controlling the specific down-regulation of this miRNA in BRAF-mutant cancers are still unclear." (PMID 29115941, 2017). "DFS was also significantly worse in patients with BRAF mutated cancers compared to wild-type BRAF by both univariate (HR 1.98, P = 0.0252) and multivariate analyses (HR 2.222)." (PMID 28583095, 2017). "This BRAFV600 mutation represents a unique target for cancer therapy and has led to the development of several specific BRAF inhibitors, amongst others vemurafenib." (PMID 28915798, 2017). "For example, limited molecular assays such as PCR and Sanger sequencing have been used to detect known cancer mutations, such as V600E in the BRAF gene." (PMID 28685150, 2017). "BRAF-mutated cancers and those that were positive for FDG uptake are often refractory to radioiodine therapy." (PMID 29085335, 2017). "The BRAF genetic mutation is present in about seven percent of all human cancers, and the most common mutation BRAFV600E is involved in various carcinomas, including metastatic melanoma, thyroid cancer, and colon cancer." (PMID 28353640, 2017). "First, we employed validated Sequenom-based genotyping for BRAF V600E, the most common cancer-associated BRAF mutation." (PMID 27812792, 2017). "Within the top five of the miRNAs screened, we validated miRNA-31 (miR-31) and miR-135b as up-regulated, while miR-193a-3p was down-regulated in BRAF-mutated cancer." (PMID 29115941, 2017). "It has been shown that KRAS and BRAF mutated cancer cells expressed more GLUT1 transporters that had led to increased uptake of vitamin C in its reduced form, dehydroascorbate (DHA)." (PMID 28791253, 2017). "This mutation occurs in the activation loop of BRAF and substantially increases kinase activity to drive the proliferation of cancer cells." (PMID 28418885, 2017). "All but two cancers found positive for TERT promoter mutations (5/7) also harbored another RAS or BRAF gene mutation." (PMID 29085338, 2017). "We also found the prevalence of BRAF mutations increased significantly at Samsung Medical Center and Holycross Cancer Center." (PMID 27793009, 2017).
cancer (continued). "Targeted genetic profiling of all polyps for 15 established cancer-associated genes (TruSight®Tumor15, Illumina) confirmed the BRAF V600E and KRAS G12D mutations in 5 (46%) and one (9%) polyps, respectively." (PMID 29213343, 2017). "The knowledge of alterations in the MAPK pathway, such as RET/PTC rearrangements and BRAF mutations, will provide oportunities for clinical development of novel treatment strategies for this cancer." (PMID 28507274, 2017). "More recently, the combination of MEK with BRAF (a human gene that encodes a protein called B-Raf) inhibitors and/or other therapies has provided a new treatment option for multiple cancers." (PMID 28954413, 2017). "BRAF-mutated cancers and those that are positive on fluorodeoxyglucose positron emission tomography scans are often refractory to radioiodine." (PMID 29108240, 2017). "BRAF mutations, by contrast, displayed inconsistent methylation patterns between cancer types in this study." (PMID 29125844, 2017). "BRAF inhibitor significantly increases the risk of developing cuSCC compared with dual BRAF/MEK inhibitors in cancer patients." (PMID 29137342, 2017). "Discovery of BRAF mutations in cancer allowed many scientists to link BRAFV600E with poor prognosis and overall survival in comparison to BRAF-WT and or RAS mutations." (PMID 28282860, 2017). "TAK-632 was initially described to have cellular activity against mutated BRAF or mutated NRAS cancer cell lines and antitumor efficacy in vivo in BRAF and NRAS mutated xenograft models." (PMID 28002790, 2017). "Activating BRAF mutations have been detected in various malignant tumors such as melanoma, papillary thyroid cancer, CRC, ovarian cancer, and hairy cell leukemia." (PMID 28583095, 2017). "In a clinical perspective, it is widely acknowledged that paradoxical ERK activation by RAF inhibitors in non-BRAF-mutated cancer cells mostly relies on BRAF and CRAF dimerization." (PMID 28497782, 2017). "It has to be added that the association of BRAF mutational status with miRNA deregulation was also confirmed in other human cancers." (PMID 28118616, 2017). "Three of the five known FTCs with the BRAF K601 mutation had minimal capsular and vascular invasion, consistent with the tendency of this mutation to be associated with low-grade cancers." (PMID 29085338, 2017). "Although there have been few evidences of miRNA directly targeting BRAF mRNA, it has been demonstrated that BRAF oncogenic mutations were associated with miRNAs deregulation in many cancer types." (PMID 26646588, 2016). "Utilizing the heterogeneous cytospins, KRAS and BRAF gene mutational status from xMD-dissected cancer cells was compared to manual macrodissected cytospin slides by pyrosequencing." (PMID 26999048, 2016). "We provide a quantitative measure for all parameters that contribute to BRAF cancer mutation frequencies by evaluating their importance using a random forest classifier." (PMID 26744778, 2016). "SSA/Ps are believed to become serrated pathway cancers via a series of molecular alternations, including BRAF mutation and CpG island methylation, with epigenetic inactivation of the mismatch repair gene MLH1 resulting in microsatellite instability." (PMID 27437153, 2016). "Mutations in well-known cancer driver genes (BRAF and H/K/NRAS) and fusion gene rearrangements were identified in 37.22%, 25.00%, and 12.78% of total tumors, respectively." (PMID 27494611, 2016). "Overall this study has identified that the E3 ubiquitin ligases, RNF43 and ZNRF3, are frequently mutated in BRAF mutant cancers of the serrated pathway, particularly those that are MSI." (PMID 27661107, 2016). "Other recurrent mutations in BRAF mutant/MSI cancers were X441fs (n=3), X370fs (n=2) and G363D (n=2)." (PMID 27661107, 2016).
cancer (continued). "This is commonly due to mutation of the APC gene which is uncommonly mutated in BRAF mutant serrated pathway cancers." (PMID 27661107, 2016). "ZNRF3 was mutated in 16/54(30%) BRAF mutant/MSI and 5/33(15%) BRAF mutant/microsatellite stable compared to 0/27 BRAF wild type cancers (p=0.004)." (PMID 27661107, 2016). "High expression of MGL ligand was correlated to BRAF mutations and altered glycosylation, which was thought to subsequently increase immunosuppression by metastasizing cancer cells." (PMID 27729614, 2016). "Point mutations were found in 5 BRAF mutant/MSI and 4 BRAF mutant/MSS cancers, and these were located along the length of the gene." (PMID 27661107, 2016). "Mutations in the gene that encodes a protein called BRAF are commonly found in certain cancers, such as melanomas." (PMID 26744778, 2016). "Cancers with a BRAF mutation are generally more aggressive than their counterparts without the mutation." (PMID 27127670, 2016). "Next, we analyzed 274 mutations in 24 cancer-relevant genes (Sequenom technology), including BRAF, NRAS, KIT c-MET, GNAS and GNAQ." (PMID 27057633, 2016). "BRAF is a serine/threonine kinase that is commonly activated by somatic point mutation in human cancer and his activity is also regulated by phosphorylation of residues in the activation segment." (PMID 27713912, 2016). "BCPAP cells are hemizygous and KTC1 cells are heterozygous for BRAF V600E; both contain several other cancer-associated mutations." (PMID 27127178, 2016). "According to our results, there was a significant association between high AJCC stage and BRAF mutation, with positive BRAF mutation status being associated with a 1.82-fold increased risk of stage III/IV cancers compared to wild-type cases." (PMID 27600854, 2016). "The high rate of mutation and structural variation in BRAF mutant cancers suggests alteration of these genes is important for progression of serrated pathway cancers, where Wnt activation by APC mutation is uncommon." (PMID 27661107, 2016). "The biomarkers close to the root node include genes in which genomic alterations frequently occur in cancers, such as BRAF mutations." (PMID 26916442, 2016). "A striking example is the oncogenic serine/threonine kinase BRAF, for which the V600E mutation in its kinase activation segment (AS) accounts for >95% of all BRAF cancer mutations." (PMID 26744778, 2016). "This is the first evidence showing that IFNγ inhibits CXCL8 secretion in a BRAF V600e mutated cancer cell line." (PMID 27555670, 2016). "To clarify the molecular and clinicopathological characteristics of colorectal serrated lesions, we assessed the DNA methylation of cancer-associated genes in a cohort of BRAF-mutant precancerous lesions from 94 individuals." (PMID 27145369, 2016). "Eight BRAF mutant/MSS cancers (8/33, 24.2%) had RNF43 mutations including 2 point mutations and 6 frameshift mutations that were located throughout the gene." (PMID 27661107, 2016). "Mutations in the phosphate-binding loop (residues 464 to 472) correspond to <1% of all BRAF mutations in cancer." (PMID 26744778, 2016). "BRAF mutant/MSS cancers had a moderate proportion of RNF43 mutations (8/33; 24.2%), whilst BRAF wild type cancers had the least frequent mutations compared to the BRAF mutant subgroups (3/79, 3.8%) (p<0.0001)." (PMID 27661107, 2016). "The results showed that cells with BRAF mutations were statistically more sensitive to the BRAF inhibitor SB590885 than cells with other mutated cancer genes (Figure." (PMID 26916442, 2016). "Patients who had received prior cancer treatment and those with wild type BRAF mutation were excluded from the study." (PMID 26767073, 2016). "BRAF mutations are found in different types of cancer, especially in those with poor prognosis, for example, in more than 60% of metastatic melanoma, 40-70% of papillary thyroid cancer, and up to 18% of CRC." (PMID 27276710, 2016).